PRXL2B (peroxiredoxin like 2B)
Description:
Catalyzes the reduction of prostaglandin-ethanolamide H(2) (prostamide H(2)) to prostamide F(2alpha) with NADPH as proton donor. Also able to reduce prostaglandin H(2) to prostaglandin F(2alpha) (By similarity).
Synonyms: PM/PGFS; C1orf93; FAM213B; MGC26818
Tractability: PROTAC: ubiquitination databases record sites on it.
Gene: Protein-coding gene on chromosome 1 (2,586,491 to 2,591,470, forward strand). Ensembl gene ENSG00000157870.
Subcellular location: Cytoplasm, cytosol
Subcellular location (Human Protein Atlas): Cytosol; Nucleoplasm
Pathways (Reactome):
Metabolism: Synthesis of Prostaglandins (PG) and Thromboxanes (TX)
Gene Ontology:
Molecular function: protein binding; oxidoreductase activity, acting on the CH-OH group of donors, NAD or NADP as acceptor; prostaglandin F synthase activity; prostaglandin H2 endoperoxidase reductase activity
Biological process: prostaglandin biosynthetic process; cyclooxygenase pathway
Cellular component: extracellular exosome; mitochondrion; cytoplasm; endoplasmic reticulum; myelin sheath; cytosol
Genetic constraint (gnomAD): Loss-of-function variants: 27 observed, 19.37 expected, observed/expected ratio (o/e) 1.39, 90% interval 1.02 to 1.85. The upper end of that interval is the gene's LOEUF score, 1.85, which puts it in group 6 of 6, group 1 being the genes least tolerant of losing a copy. Missense variants: 269 observed, 228.19 expected, observed/expected ratio (o/e) 1.18, 90% interval 1.07 to 1.3. Synonymous variants: 115 observed, 97.05 expected, observed/expected ratio (o/e) 1.18, 90% interval 1.02 to 1.38.
Homologues: Orthologues: macaque PRXL2B (95% identical), mouse Prxl2b (88% identical), pig PRXL2B (88% identical), rat Prxl2b (87% identical), guinea pig PRXL2B (86% identical), chimpanzee PRXL2B (79% identical), dog PRXL2B (61% identical).
Diseases named in the same sentence as PRXL2B in open-access papers:
PRXL2B is named in the same sentence as 3 diseases in open-access papers, as found by Europe PMC text mining. Sharing a sentence is not in itself a finding about the gene and the disease. The quoted sentences say what the papers report.
tumor (1 paper, 2022). "The accumulation of PTGES3 and PRXL2B transcripts in tumor tissue correlates with a simultaneous reduction of oncomiRs miR-223, miR-19a, miR-605, and miR-486, miR-211, miR-423, respectively." (PMID 35453789, 2022).
PRXL2B also shares sentences with these, for which no sentence is quoted: cancer (1 paper); gastric cancer (1).